ZNF683 (zinc finger protein 683)
Description:
Transcription factor that mediates a transcriptional program in various innate and adaptive immune tissue-resident lymphocyte T-cell types such as tissue-resident memory T (Trm), natural killer (trNK) and natural killer T (NKT) cells and negatively regulates gene expression of proteins that promote the egress of tissue-resident T-cell populations from non-lymphoid organs. Plays a role in the development, retention and long-term establishment of adaptive and innate tissue-resident lymphocyte T cell types in non-lymphoid organs, such as the skin and gut, but also in other nonbarrier tissues like liver and kidney, and therefore may provide immediate immunological protection against reactivating infections or viral reinfection. Also plays a role in the differentiation of both thymic and peripheral NKT cells. Negatively regulates the accumulation of interferon-gamma (IFN-gamma) in NKT cells at steady state or after antigenic stimulation. Positively regulates granzyme B production in NKT cells after innate stimulation. Associates with the transcriptional repressor PRDM1/BLIMP1 to chromatin at gene promoter regions. [Isoform 1]: Lacks transcriptional repressor activity. Binds to DNA within promoter regions of the transcriptional repressor PRDM1/BLIMP1 target sites. Unable to regulate interferon-gamma (IFN-gamma) production in cytomegalovirus (CMV)-infected effector CD8(+) T-cells. [Isoform 2]: Transcriptional repressor that binds to DNA within promoter regions of the transcriptional repressor PRDM1/BLIMP1 target sites. Regulates interferon-gamma (IFN-gamma) production in cytomegalovirus (CMV)-infected effector CD8(+) T cells.
Synonyms: Hobit; MGC33414
Tractability: No criterion of Open Targets' tractability assessment is met for any kind of drug.
Gene: Protein-coding gene on chromosome 1 (26,361,634 to 26,374,522, reverse strand). Ensembl gene ENSG00000176083.
Subcellular location: Nucleus
Gene Ontology:
Molecular function: protein binding; DNA-binding transcription factor activity; promoter-specific chromatin binding; RNA polymerase II cis-regulatory region sequence-specific DNA binding
Biological process: regulation of extrathymic T cell differentiation; regulation of gene expression; regulation of natural killer cell differentiation; regulation of NK T cell differentiation; regulation of transcription by RNA polymerase II; regulation of immune system process; regulation of multicellular organismal process
Cellular component: nucleus
Genetic constraint (gnomAD): Loss-of-function variants: 20 observed, 31.29 expected, observed/expected ratio (o/e) 0.64, 90% interval 0.45 to 0.93. The upper end of that interval is the gene's LOEUF score, 0.93, which puts it in group 3 of 6, group 1 being the genes least tolerant of losing a copy. Missense variants: 621 observed, 640.79 expected, observed/expected ratio (o/e) 0.97, 90% interval 0.91 to 1.04. Synonymous variants: 264 observed, 272.72 expected, observed/expected ratio (o/e) 0.97, 90% interval 0.88 to 1.07.
Homologues: Orthologues: chimpanzee ZNF683 (99% identical), pig ZNF683 (68% identical), guinea pig ZNF683 (55% identical), rabbit ZNF683 (54% identical). Paralogues in human: ZBTB49 (19% identical), PRDM12 (17% identical), FEZF2 (16% identical), BCL6 (16% identical), FEZF1 (15% identical), ZBTB7B (15% identical), BCL6B (14% identical), ZBTB21 (13% identical), ZBTB14 (12% identical), GFI1 (12% identical), PRDM13 (12% identical), ZBTB46 (11% identical), and 16 more.
Diseases named in the same sentence as ZNF683 in open-access papers:
ZNF683 is named in the same sentence as 28 diseases in open-access papers, as found by Europe PMC text mining. Sharing a sentence is not in itself a finding about the gene and the disease. The quoted sentences say what the papers report.
COVID-19 (3 papers, 2020 to 2021). A disease caused by infection with severe acute respiratory syndrome coronavirus 2. "Sequencing analyses of T cells isolated from the BALF of COVID-19 patients have shown that ZNF683+CD8+ T cells have the highest clonal expansion level and CCR7+ central memory T cells have the lowest." (PMID 32808850, 2020). "In addition, moderate COVID-19 cases are characterized by the presence of highly clonally expanded CD8+ T cells (e.g. ZNF683+ CD8 T cells) in contrast to severe patients." (PMID 34098950, 2021).
lung carcinoma (3 papers, 2022 to 2024). "However, a recent study suggested that ZNF683 is upregulated in neoantigen-specific TILs in lung cancer, which was consistent with our findings." (PMID 36869093, 2023). "A higher proportion of ZNF683-overexpressed TRM (ZNF683/Hobit is a characteristic gene of TRM) may become a better prognostic indicator and be associated with better immunotherapeutic response in lung cancer." (PMID 36090993, 2022). "Research has demonstrated that ZNF683+CD8+T cell totality is important for anti-tumor immunity, with high levels of this ZNF683 gene marker detected in peripheral blood samples from patients with renal cell carcinoma, melanoma, and lung cancer." (PMID 39872521, 2024). "ZNF683 expression was higher in cancer Trm cells than in noncancer Trm cells, and was also upregulated in lung cancer Trm cells." (PMID 36869093, 2023).
breast carcinoma (2 papers, 2022 to 2026). "Then based on the median expression levels of CD2, ZNF683 and KLRB1 separately, the breast cancer patients were divided into high-expressed subgroups and low-expressed subgroups." (PMID 36090993, 2022).
cytomegalovirus infection (2 papers, 2022 to 2024). A herpesvirus infection caused by Cytomegalovirus. "Previous studies showed that ZNF683 was highly expressed in patients after human cytomegalovirus (hCMV) infection, and there are 2 of 5 haplo‐SCT recipients infected with hCMV after HSCT." (PMID 39225336, 2024). "Notably, ZNF683 is necessary for IFNγ production after human cytomegalovirus infection." (PMID 35458449, 2022).
melanoma (2 papers, 2024 to 2025). A malignant, usually aggressive tumor composed of atypical, neoplastic melanocytes. "Importantly, the majority of MANA-specific TIL resided in similar TRM clusters in both cancers (84.62% for NSCLC and 59.78% for melanoma), characterized by expression of CD103, CXCL13, ZNF683, and ENTPD1 (CD39)." (PMID 39900903, 2025).
multiple myeloma (2 papers, 2022 to 2024). "On the other hand, ZNF683, known to regulated NK cell development but also involved in NK cell exhaustion in multiple myeloma, was up-regulated." (PMID 39867888, 2024).
Richter syndrome (2 papers, 2024 to 2025). Transformation of chronic lymphocytic leukemia into aggressive non-Hodgkin's lymphoma, usually diffuse large B-cell lymphoma (immunoblastic or centroblastic variant). "ZNF683, the core marker of CD8.c10, was recently proven to serve as a marker of responding Trm cells following ICI therapy in HNSCC and Richter syndrome and is indeed located at relatively early differentiation stages in TIL trajectories." (PMID 38343549, 2024). "Interestingly, the expression of ZNF683 in CD8+ T cells, a pivotal regulator of T cell activation and cytotoxicity, has been reported to correlate with a better response to anti‐PD‐1 therapy in patients with CLL and Richter Syndrome." (PMID 39777847, 2025).
Achalasia (1 paper, 2023). A disorder of esophageal motility characterized by the inability of the lower esophageal sphincter to relax during swallowing and by inadequate or lacking peristalsis in the lower half of the body of the esophagus. "We found TRM showed more expansions in achalasia than those in controls, especially in ZNF683+ CD8+ TRM and XCL1+ CD4+ TRM." (PMID 37542039, 2023). "We found TRM were increasingly infiltrated in the LES tissue in achalasia and mainly restricted to the area surrounding the myenteric plexus, especially ZNF683+ CD8+ TRM and XCL1+ CD4+ TRM." (PMID 37542039, 2023). "We show C1QC+ macrophages and tissue-resident memory T cells (TRM), especially ZNF683+ CD8+ TRM and XCL1+ CD4+ TRM, are significantly expanded and localized surrounding the myenteric plexus in the LES tissue of achalasia." (PMID 37542039, 2023). "Metascape analysis of marker genes of each TRM subcluster showed that ZNF683+ CD8+ TRM and XCL1+ CD4+ TRM, the most common types in achalasia, were enriched mainly in adaptive immune and lymphocyte activation." (PMID 37542039, 2023). "Among the TRM subclusters, XCL1+ CD4+ TRM (Th5) and ZNF683+ CD8+ TRM (Tc5), expanded remarkably in achalasia compared with controls." (PMID 37542039, 2023). "Among these DEGs, ZNF683, important for the differentiation and maintenance of TRM39, and RBPJ, central to Notch signaling and maintenance of TRM40, were highly expressed in TRM, which might explain the high infiltration of TRM in achalasia." (PMID 37542039, 2023).
AIDS (1 paper, 2022). A syndrome resulting from the acquired deficiency of cellular immunity caused by the human immunodeficiency virus (HIV). "In subsequent functional experiments, we found that ZNF683 increased the proliferation and IFNγ secretion ability of CD8+ T cells, thus decreasing SIV or HIV replication, which may be related to AIDS progression in SIVmac239-infected NPMs." (PMID 35458449, 2022).
alcohol use disorders (1 paper, 2025). "Whole‐exome sequencing of 83 alcohol use disorder patients identified 106,525 SNVs and 19,826 InDels, revealing six genes (CNTNAP3, ZNF683, ALDH2, CCHCR1, ZNF45, ESRRA) with deleterious mutations through comprehensive bioinformatics analysis." (PMID 40730494, 2025).
chordoma (1 paper, 2023). Chordomas are rare malignant tumors arising from embryonic remnants of the notochord in axial skeleton. "However, the fraction of CD8_ZNF683 T cells was decreased in recurrent chordomas." (PMID 37784253, 2023). "We infer that promoting NK and CD8_GZMK T‐cell function or inhibiting the transformation of CD8GZMK T cell to CD8_ZNF683 T cell and promoting the transformation of NKT cells to NK cells may be promising strategies for preventing chordoma recurrence." (PMID 37784253, 2023).
colorectal cancer (1 paper, 2023). A primary or metastatic malignant neoplasm that affects the colon or rectum. "We focused on zinc finger protein 683 (ZNF683) as a cancer-specific Trm cell marker and analysed its expression from single-cell RNA-seq analysis of 17,257 colorectal cancer (CRC)-infiltrating immune cells." (PMID 36869093, 2023).
hyperthyroidism (1 paper, 2024). Overactivity of the thyroid gland resulting in overproduction of thyroid hormone and increased metabolic rate. "Our study indicates that ISG15 can serve as a diagnostic biomarker for hyperthyroidism, ZNF683 can be considered as one of the diagnostic biomarkers for hypothyroidism, and elevated expression of IGHG3 suggests abnormal thyroid function in patients." (PMID 39872521, 2024). "Key signaling molecules were identified: ISG15 for hyperthyroidism, ZNF683 for hypothyroidism, and IGHG3 common to both conditions." (PMID 39872521, 2024). "The expression levels of IGHG3, ISG15, and ZNF683 were analyzed in relation to clinical examination data from patients with hyperthyroidism, hypothyroidism, and healthy individuals." (PMID 39872521, 2024). "Using clinical baseline data collected from participants and ELISA results for IGHG3, ISG15, and ZNF683, we randomly divided the samples into training and testing groups to construct prediction models for patients with AITD hyperthyroidism and hypothyroidism." (PMID 39872521, 2024).
hypothyroidism (1 paper, 2024). Abnormally low levels of thyroid hormone. "This suggests that high expression of ZNF683 may indicate that patients are in a state of hypothyroidism, highlighting ZNF683 as an important risk factor for the progress of this condition." (PMID 39872521, 2024). "Through a combined analysis of gene transcriptomics and proteomics between the hypothyroidism group and healthy controls, we identified key differential genes ZNF683 and IGHG3 in the resulting network regulatory diagram." (PMID 39872521, 2024). "Moreover, it is hypothesized that ZNF683 may make contribution to the beginning of hypothyroidism through the modulation of immune responses mediated by CD8+ T cells." (PMID 39872521, 2024).
influenza (1 paper, 2017). An acute viral infection of the respiratory tract, occurring in isolated cases, in epidemics, or in pandemics; it is caused by serologically different strains of viruses (influenzaviruses) designated A, B, and C, has a 3-day incubation period, and usually lasts for 3 to 10 days. "High levels of ZNF683/HOBIT were expressed in CMV-specific, but not in influenza-specific CD8+ T cells." (PMID 28555134, 2017).
kidney cancer (1 paper, 2015). Primary or metastatic malignant neoplasm involving the kidney. "However, there is a strong correlation between high expression of ZNF273 and ZNF683 with poor survival rates in colorectal and kidney cancers, respectively." (PMID 25994056, 2015).
myositis (1 paper, 2018). "Interestingly, we found that ZNF683 also had a higher expression in CD8+ T cells of HLA-DRB1*03-negative myositis patients when comparing PM and DM, suggesting that the expression of ZNF683 is common for both subpopulations of T cells." (PMID 30157932, 2018). "PI4KAP1 was found to have a higher expression in CD4+ T cells of HLA-DRB1*03-positive patients with myositis, and TRGC2, CTSW, HPCAL4, ZNF683, and GOLGA8B were found to have a higher expression in CD4+ T cells of HLA-DRB1*03-negative patients with myositis." (PMID 30157932, 2018). "We found that PI4KAP1 had a higher expression in CD4+ T cells of HLA-DRB1*03-positive myositis and that TRGC2, CTSW, HPCAL4, ZNF683, and GOLGA8B had a higher expression in CD4+ T cells of HLA-DRB1*03-negative myositis patients." (PMID 30157932, 2018).
oropharyngeal carcinoma (1 paper, 2022). Carcinoma, predominantly squamous cell, arising from the epithelial cells of the oropharynx. "Interestingly, our current single cell transcriptome analysis of CD8 T cells from oropharyngeal carcinomas revealed the TRM master regulator Hobit (ZNF683 gene) as differentially expressed gene in NKG2A positive T cell clusters." (PMID 34716584, 2022).
tumor (28 papers, 2021 to 2025). "Methylation profiling revealed hypermethylation of ITK and hypomethylation of ZNF683 in tumour tissues, suggesting an epigenetic basis for altered gene expression." (PMID 41301032, 2025). "The reduction of tumor‐killing GZMK+CD8+ Tem cells and the accumulation of tumor‐resident ZNF683+CD8+ Trm cells indicate substantial remodelling of CD8+ T cell populations in ICB‐resistant RCC, of which the driving factors require in‐depth investigation." (PMID 41117057, 2025). "Methylation analyses from TCGA and GEO datasets indicated hypermethylation of ITK and hypomethylation of ZNF683 in tumour samples, suggesting epigenetic regulation of these immune-related genes." (PMID 41301032, 2025). "Comparing the proportions of T/NK cells between normal and tumor groups revealed an enrichment of the four CD4+ T cell clusters, two exhausted CD8+ T cell subsets, and CD8+ZNF683+ Trm cells in the tumor group." (PMID 39093451, 2024). "pTRs after five weeks of PD-1 blockade were characterized by the activation of pre-existing CTX+ZNF683+CD8+ TILs, leading to a reduction in viable tumor tissue and associated tumor antigens." (PMID 39457649, 2024). "In cytotoxic NK cells, the expression of ADGRG1 is regulated by the transcriptional factor ZNF683, which has also been upregulated in the tumor-reactive T cells from AML." (PMID 39243082, 2024). "In our study, we found that CXCL13 was specifically upregulated in tumor-infiltrated TCR135-positive CD4+ T cells, while ZNF683 was specifically upregulated in tumor-infiltrated TCR135-positive CD8+ T cells." (PMID 38412034, 2024). "Positive associations of several TF-encoding genes such as ZNF683 (HOBIT), STAT2, and IRF3 with the abundances of tumour-infiltrating CD56bright NK and CD8+ TEM cells were observed." (PMID 39877370, 2024). "This study revealed ZNF683 as a marker for cancer-specific Trm, assuming that tumours with high Trm infiltration have a high number of cancer-specific Trm cells." (PMID 36869093, 2023). "IFN-γ and TCR signalling and ZNF683 expression are involved in Trm cell activation in tumours and are promising targets for cancer immunity regulation." (PMID 36869093, 2023). "However, in the differential gene expression analysis, the anti-WT1 T-cells exhibited higher expression of ZNF683 and S1PR, both of which have been associated with effective antitumor responses and persistence in tumor-infiltrating lymphocytes." (PMID 40847198, 2025). "One critical observation from this study was the significantly remodelled CD8+ T cells activation and development in ICB‐resistant RCCs mediated by MARCO+ TAMs, resulting in significant reduction of tumor‐killing GZMK+CD8+ Tem cells as well as accumulation of tumor‐resident ZNF683+CD8+ Trm cells." (PMID 41117057, 2025). "ZNF683 was also a marker for tumor-specific tissue-resident memory CD8+ T cells." (PMID 38412034, 2024). "ZNF683+ Trm cells play a central role in cellular immunity, especially tumour immunity." (PMID 36869093, 2023). "First, we were unable to confirm whether ZNF683+ Trm cells could recognise or attack tumours because our analysis was performed only at the gene expression level in cells." (PMID 36869093, 2023). "ZNF683+ Trm cells could play a role in tumour immunity by expressing IFN-γ." (PMID 36869093, 2023). "This signature includes key genes for maintaining cellular cytotoxicity such as ZNF683,41PRF1, IL2RB, and IFNG and immune activation and exhaustion markers including LAG3, PDCD1, PRF1, and TBX21 that contribute to anti-tumor immunity." (PMID 41045934, 2025). "Consistent with previous findings, we observed that Tcr-1-positive CD8+ subclone was identified as high expression of GNLY, ZNF683, CXCL13, and were furtherly proven of high avidity against SYT-SSX fusion-positive tumor cells." (PMID 39748060, 2025).